UCP1 (uncoupling protein 1)
Diseases named in the same sentence as UCP1 in open-access papers (continued):
Sharing a sentence is not in itself a finding about the gene and the disease.
Obesity (continued). "Notably, several pharmacological approaches promoting UCP1-mediated thermogenesis in human brown adipocytes are currently being investigated in clinical trials to mitigate obesity." (PMID 40983918, 2025). "Concurrently, exercise-induced exosomes or miRNAs from skeletal muscle may regulate the futile creatine cycle in adipose tissue and activate non-uncoupling protein 1-dependent thermogenic pathways, thus alleviating obesity conditions." (PMID 41071722, 2025). "Consequently, promoting UCP-1 expression in adipocytes has emerged as a promising strategy for treating obesity and related metabolic disorders." (PMID 41303454, 2025). "In muscle cells, UCP1 enhances mitochondrial biogenesis and functions in skeletal muscle; targeting UCP1 pharmacologically (e.g., with β3-adrenergic agonists or cold exposure) is an area of interest for combating obesity and metabolic diseases in individuals who are unable to exercise." (PMID 40277921, 2025). "Low-temperature exposure activated UCP-1-mediated thermogenesis in BAT to counteract obesity." (PMID 40400677, 2025). "Interestingly, Ucp1‐positive adipocytes are typically found in brown adipose tissue, where they promote thermogenesis and counteract obesity." (PMID 40631796, 2025). "Longitudinal tracking of brown fat activity (including uncoupling protein-1 expression), body temperature, and peripheral serotonin metabolism initiated early in the development of obesity could clarify how these systems interact over time." (PMID 41305664, 2025). "Also, increased expression of UCP1 and UCP2 genes, both of which are associated with obesity, indicates an obesity threat." (PMID 40024983, 2025). "Studies suggest that magnesium deficiency may help combat diet‐induced obesity and metabolic disorders by activating metabolic pathways, increasing BAT UCP1 mRNA expression, and raising body temperature." (PMID 40666825, 2025). "Thus, activating UCP1 is a crucial defense mechanism against obesity and related metabolic disorders." (PMID 41374084, 2025). "Moreover, the unexpected expression patterns of Fas, Ucp1/2, Hsl, and Cpt-1 highlight the complex and possibly time-dependent nature of adipose tissue remodeling in response to diet-induced obesity and probiotic intervention." (PMID 41470800, 2025). "Consistently, we found that protein expression of REGγ was negatively correlated with UCP1 in mice, indicating that REGγ might play an important role in promoting obesity." (PMID 40971725, 2025). "UCP1 is also known to contribute to protection against obesity." (PMID 39680603, 2024). "Specifically, atractylenolide II has been validated to improve obesity-induced hyperlipidemia, hepatosteatosis, and IR while simultaneously enhancing weight loss through activating adenosine 5’-monophosphate-activated protein kinase (AMPK)/PGC-1α/UCP1 axis." (PMID 39206264, 2024). "In this condition, an anti-obesity effect became evident in wild-type mice following either drug regimen that resulted in comparable levels of weight loss and BAT browning as suggested by increased UCP1." (PMID 39484996, 2024). "In addition, it was found that the anti-obesity effect of curcumin was affected when UCP1 was knocked out." (PMID 39539361, 2024). "Overall, the authors concluded that in utero exposure to DBP can increase stress in the endoplasmic reticulum, which inhibits the expression of UCP1, decreasing the energy consumption of brown adipose tissue, affecting the metabolism of lipids and sugars and leading to obesity in the offspring." (PMID 39728417, 2024). "This hypothesis is corroborated by evidence that in mice, simultaneous double calcium channel TRPV1 and uncoupling protein 1 (UCP1) knockout induces severe obesity and hypertension." (PMID 38186879, 2024). "Based on the results of protein expression, we can hypothesize that one of the mechanisms of OA regulation of obesity is the enhancement of TGR5 / UCP-1 protein expression, hence accelerating energy expenditure." (PMID 38246999, 2024).
Obesity (continued). "Moreover, a low dietary Mg intake prevents high-fat diet-induced obesity in mice by enhancing the expression of genes involved in β oxidation and by elevating Ucp1 levels in BAT, with the consequent increased thermogenesis." (PMID 39199139, 2024). "Interestingly, D-mannose rapidly activates ACSS2-PPARγ-UCP1 axis to resist high fat diet induced obesity in mice." (PMID 38332049, 2024). "Therefore AMPK activators, such as resveratrol and quercetin, have the potential to treat obesity by activating UCP1 and increasing energy expenditure." (PMID 39568820, 2024). "Thus, our results confirm that the mechanisms of action of CAP to counter HFD-induced obesity are permissive of UCP-1 in adipose tissues." (PMID 39204203, 2024). "In addition, the decrease in BAT thermogenesis of HFD-fed mice was associated with the altered expression of TGR5 and its target genes UCP1 for energy expenditure, contributing to obesity development." (PMID 38472812, 2024). "Despite a lack of studies on the effect of miR-21 role on the expression of thermogenic targets in PCOS, the use of miR-21 mimics in obesity induced by high-fat diet was associated with upregulation in multiple genes involved in thermogenesis, including PRDM16, PGC-1α, UCP1, and CIDE-A." (PMID 38987854, 2024). "They theorized that the potential anti-obesity effects of taurine might be partly due to thermogenic gene up-regulation in brown adipose tissue, such as UCP-1, Cox7a1, and Cox8b, and fat deposition down-regulation in inguinal white adipose tissue." (PMID 39539444, 2024). "Obesity reduced the proportion of people with high UCP1 expression only in the older group." (PMID 38917410, 2024). "In addition, attenuation of hypothalamic output signals that induce lipolysis in WAT and UCP1-mediated thermogenesis in BAT promotes obesity." (PMID 38317079, 2024). "Additionally, BET has a role in the regulation of glucose and lipid metabolism, and a beneficial effect on obesity via the activation of UCP-1." (PMID 38927789, 2024). "Marine algae and seaweed containing fucoxanthin have been reported to possess anti-obesity properties by increasing fat oxidation through the upregulation of UCP1 expression in white adipose tissue, increasing lipolytic enzyme activity, and suppressing obesity-related inflammation." (PMID 38613023, 2024). "Furthermore, it provides evidence supporting the involvement of P38/MAPK signaling via the PGC-1α/UCP1 pathway in mediating the anti-obesity effects of succinic acid." (PMID 39599615, 2024). "It is these effects that cause obesity-induced thermogenesis: in BAT and inguinal WAT, β3AR signaling induces PRDM16 and PGC1α via the β3AR–cAMP–PKA pathway and increases UCP1 expression in mice; PPARα and PPARγ are also involved in heat production through this signaling pathway." (PMID 39796158, 2024). "Thus, the MCU would be a significant energy source for UCP1’s thermogenic process, which would be advantageous for the management of metabolic illnesses like obesity." (PMID 38650945, 2024). "UCP1 could mediate the functions of brown and beige fat, which promote anti-obesity and anti-diabetic effects when activated." (PMID 38784133, 2024). "With regard to mitochondrial uncoupling protein 1 (UCP-1), which was previously shown to have a central role in thermogenic response in BAT and whose level was reported to decline in this organ with obesity, it was also shown that its deficiency promoted ER stress in BAT." (PMID 39160276, 2024). "Of note, M. alba L. extract was able to significantly increase the UCP1 levels downregulated in obese mice, and this may be considered one of the main mechanisms involved in the anti-obesity effects displayed by this plant extract." (PMID 37107352, 2023). "Conversely, genetic ablation of UCP1 leads to obesity and hyperglycemia." (PMID 36835254, 2023).
Obesity (continued). "As such, polyphenols that are able to target UCP1 and PPARα, and increase their expression, thus inducing thermogenesis or stimulating fatty acid oxidation, have attracted considerable interest as novel strategies for the treatment of obesity." (PMID 36835279, 2023). "There may be a growing interest in developing UCP1 activators as a therapeutic strategy to combat diabetes and obesity." (PMID 37907745, 2023). "Central infusion of exendin-4 in mice induced an increase of sympathetic activity targeting BAT, with increased UCP1 protein expression, and improved TG clearance by robustly increasing TG uptake by brown adipocytes, while this disappeared in the presence of obesity." (PMID 37378828, 2023). "Barley extracts fermented with Lactobacillus plantarum dy‐1 may be useful in the management of obesity via UCP1‐dependent mechanisms." (PMID 38455221, 2023). "Using these transgenic mice, the development of HIF inhibitors or UCP1 activators as anti-obesity drugs may be facilitated, although low sensitivity due to the penetration depth in these mice remains a major obstacle to overcome." (PMID 37907745, 2023). "We observed the paradoxical obesity resistance of HFD-fed UCP1 KO mice at ambient temperature." (PMID 37240054, 2023). "Moreover, supplementation with CTE prevented the obesity-induced decrease in the gene expression of Ucp-1, possibly indicating an increase in thermogenesis." (PMID 37239868, 2023). "The real question: do UCP1 and brown adipose tissue activity protect against obesity in humans?" (PMID 37661736, 2023). "Moreover, these mice exhibited increased white (epididymal and inguinal subcutaneous) adipose tissue UCP1 expression and browning after a cold challenge and were resistant to high-fat diet induced obesity." (PMID 37006244, 2023). "However, this possible “rescue” mechanism of female UCP1 KO mice is questionable, since high fat diet and obesity itself impairs female reproductive function." (PMID 37355753, 2023). "Therefore, it is unsurprising that the UCP1 knockout (KO) mouse is a commonly used model to investigate possible anti-obesity strategies." (PMID 37355753, 2023). "This study suggests that CPEF may exert its anti-obesity effects by promoting thermogenesis and fatty acid oxidation via inducing UCP1 and PPARα expression, and that hesperidin and neoponcirin may be responsible for these effects." (PMID 36835279, 2023). "•Enhanced amounts of UCP1 are expected to counteract obesity." (PMID 37499977, 2023). ", that showed that UCP1-ablated mice at subthermoneutral temperatures are obesity-resistant." (PMID 37499977, 2023). "Repression is caused by obesity-associated positive and negative factors that control adipocyte browning, de novo adipogenesis, mitochondrial energy metabolism, UCP1 expression and activity, and noradrenergic response." (PMID 36674862, 2023). "Our data show that hepatic SIRT6 reduces obesity by inducing UCP1 in BAT and energy expenditure." (PMID 37566087, 2023). "Induction of UCP1-mediated thermogenesis using β3-adrenergic agonist or transgenesis could reduce obesity in animals." (PMID 36720306, 2023). "Thus, they promote white adipose tissue browning, restore uncoupling protein 1 (UCP1)-dependent energy expenditure and ultimately reduce the effects of insulin resistance, dyslipidemia and hepatic steatosis caused by obesity." (PMID 37791070, 2023). "Targeting BAT to increase oxygen consumption via mitochondrial UCP1 has been studied as a strategy to prevent or treat obesity; thus, we next determined if ACOT1KO modified BAT metabolism in a manner that would increase oxygen consumption to attenuate fat weight gain during the HFD." (PMID 37561578, 2023). "Despite this, there are no confirmed pathological conditions in mice where obesity is caused by a lower activity of the brown adipose tissue thermogenic system (as compared to its total absence in the UCP1 KO mice)." (PMID 37661736, 2023).
Obesity (continued). "New strategies for obesity treatment center on the enhancement of energy expenditure via the browning of white adipocytes and the activation of brown adipocytes that has been proven to expend energy by heat production through UCP1." (PMID 37175694, 2023). "Assessing UCP1 and thermogenic gene products (e.g., MyoD1, LHX8, DIO2, PPARGC1A) in tissue materials removed during elective surgery may be used to predict obesity risk and initiate interventions to mitigate further adipose tissue expansion at an early stage." (PMID 38069028, 2023). "Several experimental settings with rodents have well shown that ablation of BAT and genetic invalidation of the UCP1-encoding gene sensitize the organism to obesity, emphasizing the negative association between BAT and obesity." (PMID 37371902, 2023). "Overall, our results show that the lack of UCP1 at the period of adiposity rebound is associated with a transcriptional landscape of obesity and adipose tissue inflammation." (PMID 38069028, 2023). "And whether these differences in UCP1 expression ascribe to the obesity resistance and impaired glucose tolerance is warranted to future studies." (PMID 36781473, 2023). "However, UCP1-dependent thermogenesis is the most studied, and significant data on its application in models of obesity have been accumulated." (PMID 36835254, 2023). "Notably, we found that BS significantly up-regulated Pgc-1α and Ucp1 mRNA expression level, indicating thermogenesis is one of the key anti-obesity mechanism of BS." (PMID 37114142, 2023). "From the data collected above, there is reason to assume that the phenomenon of diet-induced thermogenesis can be observed in mice under certain conditions, that it then is mediated via UCP1, and that a genetic reduction of UCP1 may promote obesity in mice." (PMID 37661736, 2023). "Finally, UCP1 KO mice featured obesity resistance at ambient temperature, suggesting the existence of alternative pathways of thermogenesis." (PMID 37240054, 2023). "The critical roles of UCP1 in thermoregulation and resistance to obesity have been widely studied." (PMID 36688695, 2023). "UCP1 expression hence may prevent an early adiposity rebound and the development of a BMI trajectory in childhood that may lead to obesity by adulthood." (PMID 38069028, 2023). "From the perspective of the clinical utility of our findings, the absence of UCP1 is associated with the transcription of obesity-related genes, an increase in BMI z-score, greater adipocyte volume, and elevated plasma triglycerides." (PMID 38069028, 2023). "HDAC11 inhibits the expression of UCP1 in BAT to be a novel regulator of obesity." (PMID 37244925, 2023). "This study provides in vivo evidence for the critical role of BAT mitochondrial Ca2+ homeostasis in obesity-associated hypertension and indicates that the TRPV1/UCP1/LETM1 complex may be an alternative intervention target." (PMID 35043013, 2022). "It is well established that the deficiency of the UCP1 gene is not enough to protect against diet-induced obesity (DIO), but can modulate important physiological and metabolic parameters in mice." (PMID 36068578, 2022). "Both epiWAT and ingWAT from M‐KO mice had reduced ERK phosphorylation and elevated UCP1 levels, suggesting that CD146 deletion in macrophages reduces the inflammation‐associated impairment of beige adipogenesis in obesity." (PMID 35258174, 2022). "In our studies, sex- and microbiome-dependent activation of UCP1 expression was associated with improved metabolism in DHF-fed females, suggesting that increased thermogenesis may play a role in preventing obesity and associated metabolic diseases." (PMID 36061902, 2022). "It has been reported that enforced expression of UCP1 could relieve obesity in obese animal models, while knockdown of UCP1 in mice results in obesity." (PMID 35154681, 2022).
Obesity (continued). "They examined the regulatory role of ST32db in the β3-adrenoceptor (β3-AR)/protein kinase A(PKA)/p38 pathway and tried to explain the anti-obesity effect of ST32db in terms of this pathway, because a prior study pointed out that it is an important mechanism for the induction of UCP1 in WAT browning." (PMID 35326476, 2022). "The regulation of cytokine secretion from abdominal adipocytes, the infiltration of macrophages into adipose tissue, and the induction of uncoupling protein 1 (UCP1) production in abdominal white adipose tissue (WAT) are important components in the prevention of obesity." (PMID 36432455, 2022). "The anti-obesity effects of curcumin were not exhibited in UCP1-deficient mice, implicating the involvement of UCP1-dependent thermogenesis." (PMID 36012714, 2022). "Therefore, the potential mechanismof a SCMN patch targeting BAT against obesity development contributedto the acceleration of UCP1-dependent energy dissipation, leadingto the subsequent suppression of remote fat accumulation." (PMID 36281715, 2022). "GM mediates the action of curcumin using the UCP-1 pathway to prevent and treat obesity." (PMID 36161997, 2022). "Similarly, obesity impairs beige adipogenesis by downregulating the expression of uncoupling protein 1 (UCP-1)." (PMID 35889860, 2022). "This study provides insights into the regulation of UCP1 gene expression in a human-brown-adipocyte model under diverse nutritional conditions, which would be useful in identifying drug targets for the treatment of obesity." (PMID 35805122, 2022). "In the present paper, we aimed at evaluating the capability of these two molecules in orchestrating stem cell differentiation towards the beige phenotype, with particular attention to the main adipogenic markers and UCP1 expression, as a potential therapeutic strategy to counteract obesity." (PMID 35734882, 2022). "B6 mice are an inbred strain used to study obesity, a trait associated with BAT, while A/J mice are another strain with susceptibility to obesity and, together with B6 mice, have shown regional differences after adrenergic stimulation of UCP1." (PMID 35622774, 2022). "Furthermore, manipulation of UCP1 expression has been shown to reduce obesity improving insulin sensitivity." (PMID 35734882, 2022). "FCX shows a higher anti-obesity effect when it is administered together with medium-chain triacylglycerols (MCT) than FCX alone in diabetic/obese KK-Ay mice with increased expression of Ucp1 in WAT." (PMID 35684079, 2022). "The white adipose tissue (WAT) is the major energy storage tissue, whereas brown adipose tissue (BAT) dissipates excess energy to generate heat through the action of mitochondrial uncoupling protein-1 (UCP-1), thereby protecting against hypothermia and obesity." (PMID 35592783, 2022). "Moreover, we further used UCP1 knockout (UCP1 KO) mice to evaluate the contribution of UCP1-dependent thermogenesis in the anti-obesity effects of CQA." (PMID 36517893, 2022). "Furthermore, miR‐34a has been found to be increased which is associated with obesity and inhibit fat cell browning; Downregulation of miR‐34a can elevate expression of FGF21 and results in induction of the browning genes Ucp1, Pgc‐1, and Prdm16." (PMID 36062491, 2022). "Although UCP1-ablated mice do not spontaneously develop obesity, they are more susceptible to high-fat feeding and prone to gain fat adiposity." (PMID 35214069, 2022). "The increased UCP1 expression in the iWAT is well known as a mechanism that impacts energy balance and glucose uptake, and by which agents induce browning to prevent human obesity and related diseases." (PMID 35456900, 2022). "Indeed, H. polygyrus has been shown to attenuate obesity via upregulation of uncoupling protein 1 (Ucp1) increasing energy expenditure and lipolysis in adipose tissue." (PMID 36045216, 2022).